VEGFA (vascular endothelial growth factor A)
Diseases named in the same sentence as VEGFA in open-access papers (continued):
Sharing a sentence is not in itself a finding about the gene and the disease.
cancer (continued). "Next, we grouped them into cytokines associated with pre-cancer or the initiation stage of HCC (IL-6, TGF-β, MCP-1, FGF2, IL-2, IL-8, IL-12p40, IL-12p70, IL-18, IP-10, TNF-α, and IFN-γ), the early stage of HCC (OPN, GDF-15, RANTES, and VEGFA), and the advanced stage of HCC (IL-10, and MIP-3)." (PMID 41219858, 2025). "Notably, the recruitment mechanisms (CCL15 vs CXCL5/CXCL1/8) and effector molecules (VEGFC-dominant vs MMP9/VEGFA-cooperative) display cancer-type specificity, suggesting evolutionary selection for distinct molecular implementations of a conserved TANs-lymphatic metastasis principle." (PMID 40739091, 2025). "However, it is widely acknowledged that the role of VEGFA in cancer extends beyond angiogenesis." (PMID 38716237, 2024). "Under hypoxic conditions, circ‐ZNF609 in EVs of ESCC elevates VEGFA (vascular endothelial growth factor A) by decreasing miR‐150‐5p levels and directly binds to HuR protein to inhibit the translation of ZO‐1, Occludin, and Claudin‐1 mRNA, thereby exacerbating cancer progression." (PMID 39584047, 2024). "Therefore, understanding the regulatory mechanisms of VEGFA expression in CRC may lead to vital breakthroughs for novel therapies to fight various cancers." (PMID 36672201, 2023). "Moreover, these genes may be involved in VEGFA-VEGFR2 signaling pathway of classical cancer angiogenesis." (PMID 37467193, 2023). "Therefore, the expression of VEGFA in METTL3-silenced cancer cells was investigated." (PMID 38001065, 2023). "However, in CMP cell clusters the cancer VEGFA expression was significantly lower than normal." (PMID 37822927, 2023). "In addition, VEGFA promotes the migration of monocytes and endothelial cells through interaction with various extracellular ligands and induces the migration and invasion of cancer cells." (PMID 35457039, 2022). "Therefore, the prevention of angiogenesis through the inhibition of AKT1 and VEGFA could be an effective treatment strategy for many types of cancers." (PMID 35646655, 2022). "Because the inhibition of VEGFA signaling interferes in the angiogenesis process, and miRNAs may provide a potential anti-angiogenesis therapy for cancer treatment, we evaluated the expression of VEGFA in HCC cell lines upon treatment with miR-612 and miR-637 mimics and miR-874 inhibitors." (PMID 35205327, 2022). "Indeed, one of the genes we identified as non-mutated is VEGFA, which is known to be involved in promoting cancer angiogenesis." (PMID 35619151, 2022). "In addition, VEGFA can also be released by cancer and stromal cells." (PMID 35845599, 2022). "Moreover, silencing PRMT3 inhibited VEGFA expression of cancer cells." (PMID 34753906, 2021). "We asked if the cancer EVs that carried abundant VEGFA mRNA could activate angiogenesis." (PMID 33921957, 2021). "In addition, anoikis-resistant cancer cells display high expression of vascular endothelial growth factor A (VEGFA) and facilitate angiogenesis compared to their parental cells, supporting that the acquisition of anoikis resistance is a critical prerequisite event for metastasis." (PMID 33435156, 2021). "In addition, NEAT1 was found to inhibit the apoptosis of HemECs, thereby contributing to HA progression, by interacting with miR-361-5p to upregulate the expression of VEGFA, an essential factor in promoting cancer progression by increasing the proliferation and migration of cancer cells 100,101." (PMID 34512157, 2021). "In order to explore whether the overexpression of these genes was related to hypoxia-inducible factor (HIF), we detected HIFα and its downstream proteins vascular endothelial growth factor A (VEGFA) and glucose transporter 1 (Glut1) in VHL mutated carcinoma and para-carcinoma tissues." (PMID 33828526, 2021). "Thus, our finding that MEQ inhibited the expression of VEGFA in TNBC through the MTA2/SerRS/VEGFA pathway revealed the underlying mechanism for isoflavones and their derivatives, allowing the optimization of this natural molecule for cancer treatment." (PMID 32944400, 2020).
cancer (continued). "The VEGFA/VEGFR-2 signal transduction leads to endothelial cell proliferation, migration, survival and new vessel formation involved in angiogenesis, and has been implicated in pathogenesis of several diseases, e.g., inflammation, cancers, ophthalmic diseases, and neurological diseases." (PMID 33304904, 2020). "However, these cells maintain active the same VEGFA-activated pathways by the upregulation of others alternative TRK receptor ligands (i.e. FGF2, PDGFD and KITLG) that have been implicated in the development and drug resistance in other cancer types." (PMID 34316686, 2020). "Thus, down-regulation of either MMP9 or VEGFA expressions could further suppress the metastatic potential and angiogenic of cancer cells." (PMID 30728391, 2019). "Vascular endothelial growth factor A, VEGF-A (commonly referred as VEGF), is a multifunctional signal protein, which works as an important regulator of both physiological and pathological angiogenesis and has been related to a variety of pathologies, such as cancer and cardiovascular diseases (CVD)." (PMID 31419243, 2019). "Thus, GCNT3 role in cell invasion and drug resistance could be mediated through VEGFA in these two different cancer models, CRC and EOC, with relevant clinical implications." (PMID 29855486, 2018). "Although VEGFA has been shown to drive cancer metastasis, mechanisms thereof are largely unknown." (PMID 28504716, 2017). "As shown, the association between the VEGFA promoter and the HIF1-alpha binding region appeared constitutive in both normal B and leukemic cells, whereas the interactions of both regions with the ESSE-containing region were significantly stronger (p-value = 1.1E-14) in cancer." (PMID 26886256, 2016). "We analysed the genotypes of five SNPs of the VEGFA gene, rs699947 (–1540C>A), rs833061 (–460T>C) rs2010963 (405C>G), rs3025039 (936C>T) and rs25648 (1032C>T), on the basis of their previous description as genetic markers in other cancers and/or their potential effect on gene expression." (PMID 24971577, 2014). "Moreover, high VEGFA levels tended to correlate with worse cancer-specific survival." (PMID 22895562, 2012). "Moreover, high VEGFA levels also tended to correlate with worse cancer-specific patient survival." (PMID 22895562, 2012). "CircRNAs can act as competing endogenous RNAs (ceRNAs) that sequester anti-angiogenic miRNAs and thereby relieve repression of VEGFA/VEGFR2; this mechanism has been experimentally demonstrated in cancer models." (PMID 41516402, 2026). "Moreover, previous studies showed that the modulation of hypoxia-inducible factors and vascular endothelial growth factor A might contribute to the activation of downstream signaling pathways involved in cancer progression and related processes such as neovascularization." (PMID 39888575, 2026). "Genes upregulated in cancer cells from all 10 ccRCC tumors included the classical HIF target genes CA9 and VEGFA, as well as the atypical mitochondrial subunit NDUFA4L220." (PMID 39792555, 2025). "By improving the interaction between tumor cells and macrophages, the VEGFA/NRP-1/GAPVD1 axis facilitates the growth and cancer stemness of TNBC." (PMID 39858015, 2025). "Beyond activating VEGFA, HIF-1α upregulates glycolytic enzymes such as GLUT1 and LDHA, forcing cancer cells to adopt the Warburg effect for energy production." (PMID 40606973, 2025). "Our data showed the presence of these cytokines in fibroblast monocultures, with significantly higher levels of VEGFA and TGF‐β in PDFs, cells educated in situ, indicating their activated, and cancer‐promoting capabilities." (PMID 40411295, 2025). "Soluble inhibitors, such as B-cell maturation antigen (BCMA) and vascular endothelial growth factor A (VEGF-A), can impair the functionality of CAR-T cells, which are designed to target and eliminate cancer cells." (PMID 39996811, 2025).
cancer (continued). "Several of the identified miRNAs directly targeted cancer-relevant genes such as PTEN, VEGFA, and BCL2, and five of them overlapped with the validated set, strengthening their consistency across analyses." (PMID 41226027, 2025). "In our studies, we generated and characterized HER2-VEGFA BsAbs to enable co-phagocytosis of VEGFA with HER2-overexpressing cancer cells through simultaneous binding to HER2 and VEGFA." (PMID 40906526, 2025). "Their research indicated that some epigenetic drivers, like regulatory regions of ABCC1 and VEGFA, appeared in pan-cancer, while some epigenetic regulators, like FGF19, ASAP2 and EN1, and the PBX3 motif, are cancer specific." (PMID 40041484, 2025). "Previous studies have documented the biological and clinical significance of VEGF family members (VEGFA, VEGFB, VEGFC, and VEGFD) in lymphangiogenesis and LN metastasis in various cancer types." (PMID 40492378, 2025). "Recruited Tregs secrete vascular endothelial growth factor A (VEGFA), which enhances the stemness and progression of cancer stem cells, while also promoting angiogenesis." (PMID 41268299, 2025). "The visibility of tissue sections was evident, with a notable increase in VEGFA and PLK2 expression in ITM (n = 25) and IE2 (n = 1) cancer tissues compared to the ID group (n = 24)." (PMID 39865865, 2025). "The repurposing of vascular endothelial growth factor A (VEGF) inhibitors, originally formulated for cancer therapy, changed DR therapy outcomes from vision preservation to vision improvement." (PMID 41176546, 2025). "The top 13 GDF6-related target genes (such as VEGFA, FLT1, and KDR) showed positive correlations with the tissue expression in various cancer types, suggesting a conserved regulatory network." (PMID 40699648, 2025). "The secretion of IL-2, IL-5, IL-8, MCP-1, and VEGFA was significantly reduced in both the sh-MMP28-1 and sh-MMP28-2 AsPC-1 and BxPC-3 cancer cell lines." (PMID 39972459, 2025). "Cytoskeletal regulators (MYL9, TAGLN) and transcription factors (SNAI2) promote EMT and cancer stemness, while PMEPA1, IL6, IL8, IGFBP3, INHBA, and VEGFA contribute to proliferation, angiogenesis, and immune modulation." (PMID 41009714, 2025). "Cancer neoangiogenesis is mainly mediated through the VEGFA/VEGFR2 axis, making VEGFA and VEGFR2 key targets for the development of novel drugs." (PMID 39915447, 2025). "The MIDN level was correlated with several immune checkpoint genes, such as VEGFA, and RNA modification genes such as YTHDF1, YTHDF2, YTHDF3, and YTHDC1 in cancers." (PMID 40002690, 2025). "Among the various downstream targets, vascular endothelial growth factor A (VEGF-A) is a key regulator of angiogenesis in both health and cancer." (PMID 39960347, 2025). "We observed a significant increase in the expression of cancer stem cell markers, including CD44, VEGFA, ITGB1, ALDH1A3, SOX9 and NECTIN4, and enrichment in stemness-related pathways, such as the hedgehog, PI3K-AKT-mTOR, and WNT signaling pathways." (PMID 38892065, 2024). "The expression of PTK2, USP19, LAMC2, VEGFA, EPHA2, and MMP2 varies greatly among different cancer samples and has relatively high expression." (PMID 38694917, 2024). "Cell‐cell signaling pattern between basal cancer cells (Ca), FPCS, and TPCS revealed that while Ca‐Ca and Ca‐FPC signaling mainly comprised PGF, TGFA, and VEGFA signaling, TPCS uniquely received BMP signals (BMP2/4 and GDF5) from Ca." (PMID 38582099, 2024). "The findings showed that deletion of VEGFA resulted in increased expression of PTEN, an inhibitor of pathways that promote cancer, as well as decreased expression of the members (MEK1/2 and AKT) of MAPK and the member (SMAD2) of TGFβ signaling pathways." (PMID 39457390, 2024).
cancer (continued). "Consistent with previous preclinical cancer reports that AB0023 is anti-angiogenic and anti-metastatic, we identified a significant reduction in VEGFA and fibronectin within the conditioned media of 3D spheroids treated with AB0023." (PMID 39173635, 2024). "It has been reported that the downstream genes of ZAFS1/miR-150 includes VEGFA, ST6GAL1, ZEB1 and RAB9A in cancer cells [16,]." (PMID 39296014, 2024). "Our findings indicated a significant relationship between LOXL2 expression and the majority of the genes in immune checkpoint pathways, like VEGFA, CD276, TGFB1, and IL10 in pan-cancer." (PMID 38922489, 2024). "The angiogenesis markers VEGFA, VEGFC and VEGFD were expressed in the cytoplasm of the cancer cells." (PMID 39557919, 2024). "FOS showed positive correlations with critical genes such as VEGFA and TGFB1, indicating its possible role in immune regulation and cancer progression." (PMID 39063239, 2024). "VEGFA correlated with Contrast T2WI, and Sum average T2WI in high grade and low-grade cancers, respectively (0.517 and 0.606, respectively)." (PMID 38791417, 2024). "It is well known that PI3K/AKT/mTOR signaling pathway plays a crucial role in cancer cell proliferation, survival, metastasis and angiogenesis, and AKT and mTOR are both downstream targets of VEGFA." (PMID 38429756, 2024). "Highlighting the significance of interactions with extracellular growth factors such as VEGFA and IGF1 in cancer growth and progression, several targets, including CCND1, WEE1, VEGFA, and CDK6, were identified to interact with two miRNAs." (PMID 39614097, 2024). "It enhances cancer cell invasiveness by regulating the JAK2/STAT3 signaling pathway and facilitates angiogenesis in the TME by upregulating vascular endothelial growth factor A (VEGFA) expression." (PMID 39506843, 2024). "The non-immune cells included endothelial cells (PVALP and PECAM1), CAFs (COL1A1 and COL1A2), and cancer cells (KRT18 and VEGFA)." (PMID 38216635, 2024). "We identified several potential CHI3L1 target proteins, including VEGFA, TGF-β1, Cluster of Differentiation 74 (CD74), IL-6, inhibitor of DNA binding 3 (ID3), MMP9, CXCL8, and SPP1, in this type of cancer." (PMID 38177294, 2024). "VEGFA (Vascular endothelial growth factor-A) is a member of the VEGF family and a key mediator of angiogenesis in cancer." (PMID 39596828, 2024). "When investigating the relationship between immune checkpoint expression and PSME3, we observed that among the 33 cancers, CD276 and CD274 exhibited the highest positive correlation with PSME3, followed by VEGFA, HMGB1, THR4, BTNA2, and ENTDD1." (PMID 38312840, 2024). "Vascular endothelial growth factor A (VEGF-A) acts as an important ligand involved in the homeostasis maintenance of adult organs and plays a significant role in cancer development." (PMID 39690423, 2024). "As a suppressor of some cancer-enhancing signals, PTEN expression is negatively correlated with VEGFA expression." (PMID 39457390, 2024). "Our data showed that RO extracts significantly decreased the quantities of TNFα, VEGFa, COX-2, and MMP2 in A549 cancer cells in combination with 5-FU." (PMID 38918540, 2024). "Immunotherapeutic approaches for advanced GC, widely employed among others, include ICIs, adoptive cell therapy, antibodies targeting vascular endothelial growth factor A (VEGFA), cancer vaccines, and chimeric antigen receptor (CAR) T-cell therapy." (PMID 38339311, 2024). "These marker genes represent multiple malignant phenotypes of cancer, including tumorigenesis (EGFR, MYC), cell invasion (ITGB1 and VIM), and angiogenesis (VEGFA), among others." (PMID 38191424, 2024). "The migratory subtype also exhibits similar characteristics to those of cancer stem cells (CSC) with expression of known CSC markers (CD44, SOX9, ALDH1A3 and VEGFA) and those for tissue migration, angiogenesis, EMT and the TNFA pathway." (PMID 38892065, 2024).
cancer (continued). "Secondly, it exerts a pro-cancer effect by activating the JAK2-STAT3 pathway, which upregulates VEGFA." (PMID 39247606, 2024). "Some essential classic cancer hallmarks for cancer development were enriched during OSCC initiation, including VEGFA and TGFβ signaling, which were expressed in most cell types from scRNA-seq data." (PMID 36914617, 2023). "Some epigenetic drivers appeared in multiple cancers (for example, regulatory regions of ABCC1 and VEGFA; GATA6 and FOX-family motifs), whereas others were cancer specific (for example, regulatory regions of FGF19, ASAP2 and EN1, and the PBX3 motif)." (PMID 37914932, 2023). "Overall, the transcriptome and staining results demonstrated that VEGFA and TGFβ1 signalings, two hallmarks of full-blown cancer, have essential roles in OSCC initiation, with a spatial-switching regulation of VEGFA surrounding the DN stages." (PMID 36914617, 2023). "Thousands of mRNAs are ELAVL1 targets, including factors fostering diverse cancer traits such as proliferation (cyclins A2, B1, D1, and E1), angiogenesis (HIF1a, PTGS2, and VEGFA), survival (BCL2 and MCL1), and invasion (MMP9 and SNAI1)." (PMID 37298909, 2023). "First, we observed that DVL2 directly regulates expression of genes involved in cancer hall marks, CCND1, VEGFA and POU5F1." (PMID 36809986, 2023). "From the functional annotation analysis, CDKN2A, VEGFA, PTGS2, and STAT1 were involved in cancer pathways (hsa05200; KEGG pathway)." (PMID 36765810, 2023). "Several studies on different cancers are focusing on the major VEGFR2 ligand status, meaning VEGFA gene copy number and protein overexpression, as a prognostic marker and predictor of response to anti-angiogenic therapy." (PMID 37893095, 2023). "Among the tumorigenesis-associated genes, KEGG analysis revealed that the upregulated genes, including SLC7A5, E2F1, HIF1A, VEGFA, and EGFR, were predominantly related to central carbon metabolism in cancer, the cell cycle, and the HIF-1 signaling pathway." (PMID 37328520, 2023). "They include the VEGFA-VEGFR2 signaling pathway, MicroRNAs in cancer, and the hemostasis and relaxin signaling pathway." (PMID 37686696, 2023). "The survival analysis showed that VEGFA and placental growth factor (PGF) were correlated with poor prognosis in many cancers, including kidney renal cell and liver hepatocellular carcinoma." (PMID 37852616, 2023). "The IL-6/STAT3 signaling pathway upregulates factors involved in cancer cell proliferation (MYC, cyclin D1), angiogenesis (VEGFA, PDGF), and apoptosis (Bcl-XL)." (PMID 36720310, 2023). "Trastuzumab and bevacizumab are specific to human epidermal growth factor receptor 2 (HER2) and vascular endothelial growth factor A (VEGFA), respectively, and are used for the treatment of different cancers." (PMID 37764213, 2023). "Almost all cancers showed a significant relationship between MRPL13 and immune checkpoint suppressor genes, such as VEGFA, CD274 (PD-L1), and CTLA4." (PMID 37827692, 2023). "LA-TAMs also participated in the modification of cancer cells by SPP1, VEGFA, RETN, GRN, ADGRE5, and HBEGF secretion." (PMID 37649596, 2023). "SPARC+ T cells highly expressed the genes responsible for extracellular matrix formation, SPARC, VEGFA, A2M and COL4A126, thus implicating an important role in cancer development and metastasis." (PMID 37550396, 2023). "Immunoblot analysis of protein expression level in tumors showed that tumors induced by cancer cells stably expressing STK24+shnc had higher STAT3 and VEGFA expression levels as compared with to tumors induced by cancer cells stably expressing vector+shnc." (PMID 36720310, 2023). "The expression cor-relationships between METTL3 and its targets, including JAK1, VEGFA, CCND1, and STAT3, was positive in almost all analyzed cancer types." (PMID 38001065, 2023).